OR6C65 (olfactory receptor family 6 subfamily C member 65)
Description:
Odorant receptor.
Tractability: Antibody: UniProt places it where antibodies can reach, with medium confidence; UniProt predicts a signal peptide or a membrane-spanning region; its Gene Ontology location is reachable by antibodies, with medium confidence.
Gene: Protein-coding gene on chromosome 12 (55,400,529 to 55,401,467, forward strand). Ensembl gene ENSG00000205328.
Subcellular location: Cell membrane
Pathways (Reactome):
Sensory Perception: Expression and translocation of olfactory receptors
Gene Ontology:
Molecular function: olfactory receptor activity; G protein-coupled receptor activity
Biological process: detection of chemical stimulus involved in sensory perception of smell; G protein-coupled receptor signaling pathway
Cellular component: plasma membrane; membrane
Genetic constraint (gnomAD): Missense variants: 314 observed, 322.06 expected, observed/expected ratio (o/e) 0.97, 90% interval 0.89 to 1.07. Synonymous variants: 104 observed, 110.59 expected, observed/expected ratio (o/e) 0.94, 90% interval 0.8 to 1.11.
Homologues: Orthologues: mouse Or6c65 (83% identical), rat Or6c66b (82% identical). Paralogues in human: OR6C76 (74% identical), OR6C75 (72% identical), OR6C74 (69% identical), OR6C6 (67% identical), OR6C70 (67% identical), OR6C2 (65% identical), OR6C4 (65% identical), OR6C1 (64% identical), OR6C3 (64% identical), OR2AP1 (61% identical), OR6C68 (60% identical), OR6F1 (47% identical), and 6 more.